TPM4 (tropomyosin 4)
Description:
Binds to actin filaments in muscle and non-muscle cells. Plays a central role, in association with the troponin complex, in the calcium dependent regulation of vertebrate striated muscle contraction. Smooth muscle contraction is regulated by interaction with caldesmon. In non-muscle cells is implicated in stabilizing cytoskeleton actin filaments (By similarity). Binds calcium. Plays a role in platelet biogenesis.
Synonyms: BDPLT25; HEL-S-108
Tractability: PROTAC: ubiquitination databases record sites on it; its protein half-life has been measured.
Gene: Protein-coding gene on chromosome 19 (16,067,021 to 16,103,011, forward strand). Ensembl gene ENSG00000167460.
Subcellular location: Cytoplasm, cytoskeleton
Subcellular location (Human Protein Atlas): Actin filaments; Cytosol
Pathways (Reactome):
Muscle contraction: Smooth Muscle Contraction; Striated Muscle Contraction
Disease: Signaling by ALK fusions and activated point mutants
Signal Transduction: RHOV GTPase cycle
Gene Ontology:
Molecular function: protein binding; actin filament binding; calcium ion binding; identical protein binding; protein heterodimerization activity; protein homodimerization activity; structural constituent of muscle
Biological process: osteoblast differentiation; platelet formation; actin filament organization; muscle contraction
Cellular component: extracellular exosome; focal adhesion; membrane; stress fiber; actin filament; cytoskeleton; cytosol; muscle thin filament tropomyosin; cortical cytoskeleton; cytoplasm; podosome
Genetic constraint (gnomAD): Loss-of-function variants: 16 observed, 30.34 expected, observed/expected ratio (o/e) 0.53, 90% interval 0.36 to 0.8. The upper end of that interval is the gene's LOEUF score, 0.8, which puts it in group 3 of 6, group 1 being the genes least tolerant of losing a copy. Missense variants: 234 observed, 274.78 expected, observed/expected ratio (o/e) 0.85, 90% interval 0.76 to 0.95. Synonymous variants: 117 observed, 111.34 expected, observed/expected ratio (o/e) 1.05, 90% interval 0.9 to 1.23.
Homologues: Orthologues: guinea pig TPM4 (98% identical), rat Tpm4 (98% identical), mouse Tpm4 (86% identical), zebrafish tpm4a (81% identical), zebrafish tpm4b (79% identical), tropical clawed frog tpm4 (78% identical), Caenorhabditis elegans lev-11 (51% identical), Drosophila melanogaster Tm1 (51% identical), Drosophila melanogaster Tm2 (46% identical). Paralogues in human: TPM2 (74% identical), TPM1 (72% identical), TPM3 (72% identical).
Diseases named in the same sentence as TPM4 in open-access papers:
TPM4 is named in the same sentence as 98 diseases in open-access papers, as found by Europe PMC text mining. Sharing a sentence is not in itself a finding about the gene and the disease. The quoted sentences say what the papers report.
breast carcinoma (10 papers, 2012 to 2025). "Higher TPM4 was reported to be associated with more malignant characteristics in most cancers, including oral squamous cell carcinoma, breast cancer, lung cancer, and hepatocellular carcinoma as well as ovarian cancer." (PMID 36138856, 2022). "In addition, low TPM4 expression is associated with poor prognosis in breast cancer patients." (PMID 28431393, 2017). "TPM4 was reported to promote tumor invasion, migration, and metastasis in lung cancer, hepatocellular carcinoma, and breast cancer." (PMID 36138856, 2022). "To investigate the relationship between progression of breast cancer and tropomyosin isoforms, we interrogated the expression of TPM4 in breast cancer patients." (PMID 28431393, 2017). "TPM4 has been reported as an oncogene across different malignancies, including oral squamous cell carcinoma, breast cancer, lung cancer, hepatocellular carcinoma, and ovarian cancer, while in uterine cervix cancer and colon cancer, higher TPM4 indicated a better prognosis." (PMID 36138856, 2022). "TPM4 has been reported to be differentially expressed in breast cancer." (PMID 23594586, 2013). "Notably, established protein biomarkers for metastatic breast cancer, such as EGFR, HSPD1, PRDX6, and TPM4, which are related to lymph node and regional metastasis, were also detected." (PMID 32489334, 2020). "This is supported by our experimental validation of opposing expression patterns for TPM4 gene isoforms in non-oncogenic and oncogenic tissue samples from breast cancer patients." (PMID 23594586, 2013). "To further validate opposing transcript expression in patient samples between non-oncogenic and cancer tissues, we selected the TPM4 gene in breast cancer as an example." (PMID 23594586, 2013). "Tropomyosin 4 (TPM4), a member of the tropomyosin family, has been widely reported across different malignancies, including oral squamous cell carcinoma (OSCC), breast cancer, lung cancer, hepatocellular carcinoma (HCC), ovarian cancer, uterine cervix cancer, and colon cancer." (PMID 36138856, 2022).
lung cancer (9 papers, 2012 to 2025). A malignant neoplasm involving the lung. "In lung cancer, tropomyosin 4 has been reported to promote cell migration and such effects were due to increased F-actin assembly with tropomyosin 4 overexpression." (PMID 35804897, 2022). "The ability of TPM4 to promote cell motility and migration is reported in lung cancer, and it has been known that TPM4 overexpression in HCC tissues aggravated the malignancy of hepatocarcinoma through the negative regulation of SUD-2." (PMID 34575979, 2021). "TPM4 is able to promote cell migration modulating F-actin assembly in lung cancer, moreover, high levels of TPM4 have been detected in HCC patients with distant metastasis." (PMID 34575979, 2021). "By changing actin cytoskeleton, TPM4 enhances the migration of tumor cells in lung cancer." (PMID 33390785, 2021). "In addition to TFG-ALK in lung cancer, some ALK fusions have been reported without histopathological evidence: TPM4-ALK in esophageal squamous cell carcinoma and EML4-ALK in colon and breast carcinomas." (PMID 22347464, 2012).
glioma (8 papers, 2022 to 2025). A benign or malignant brain and spinal cord tumor that arises from glial cells (astrocytes, oligodendrocytes, ependymal cells). "Univariate logistic regression analysis confirmed the association between high TPM4 expression and adverse clinicopathological features in glioma patients." (PMID 36639743, 2023). "Collectively, these results suggest that high TPM4 expression is significantly associated with glioma development." (PMID 36639743, 2023). "The Kaplan–Meier curve indicated that high TPM4 expression was closely associated with worse OS in glioma patients." (PMID 36639743, 2023). "Next, we further verified that high TPM4 expression was an independent risk factor for glioma patients by Cox regression analysis." (PMID 36639743, 2023). "Our study aimed to evaluate the diagnostic and prognostic characteristics of TPM4 in glioma and its correlation with immune infiltration." (PMID 36639743, 2023). "Considering our findings that multiple immune-related mechanisms are associated with TPM4 expression and glioma, we next explored the tumor microenvironment (TME)." (PMID 36639743, 2023). "In order to further explore the potential role of TPM4 in the EMT phenotype of gliomas, we evaluated the co-expression association between TPM4 and EMT biomarkers." (PMID 36138856, 2022). "Specifically, in glioma, many types of TILs were associated with TPM4 expression." (PMID 36639743, 2023). "In addition, we found that TPM4 expression in glioma is closely associated with immunity, which provides a new direction and insight to promote the development of new immunotherapy strategies and treatment options for glioma patients." (PMID 36639743, 2023). "Bioinformatic analysis was performed to determine whether TPM4 has diagnostic and prognostic value for glioma." (PMID 36639743, 2023). "Totally, these results suggested that the abnormal expression level of TPM4 (As the disease progresses, TPM4 increases) in glioma was mainly attributed to the increased expression of TPM4 in tumor cells and macrophages and associated with tumor progression and macrophage polarization." (PMID 36138856, 2022). "Consequently, we explored the gene functions associated with TPM3 and TPM4 in glioma." (PMID 35892971, 2022). "The upregulation of TPM4 predicts shorter survival time in glioma patients and plays a crucial role in the pro-EMT process through synergistic interactions with the pro-EMT signalling pathway and key molecules." (PMID 40365337, 2025). "The following databases and analytical tools were used to explore the clinical significance of TPM4 in glioma: TCGA, GTEx, GEO, STRING, and TISIDB." (PMID 36639743, 2023). "We discovered that high TPM4 expression was often related to worse clinicopathological features in gliomas." (PMID 36639743, 2023). "Overall, our study demonstrates that TPM4 can serve as a biomarker for glioma prognosis and diagnosis." (PMID 36639743, 2023). "Our results demonstrate that TPM4 expression is related to multiple immune markers and levels of immune infiltration in glioma." (PMID 36639743, 2023). "We discovered that TPM4 mRNA was significantly upregulated in glioma tissues compared to healthy tissues (P < 0.001)." (PMID 36639743, 2023). "We found that TPM4 is related to the molecular targets of glioma, such as CD160, IDO1, IL10, KDR, PVRL2, and TGFB1." (PMID 36639743, 2023). "In recent years, the abnormal expression of TPM4 was investigated in multiple malignancies, invasive breast cancer, colon cancer, glioma, hepatocellular carcinoma, lung cancer, and ovarian cancer." (PMID 36993958, 2023). "Kaplan–Meier analysis indicated that high expression of TPM4 in glioma correlated with poor prognosis." (PMID 36639743, 2023). "In our study, we first determined the expression of TPM4 in whole WHO grade of glioma patients using the TCGA database." (PMID 36639743, 2023).
glioma (continued). "Subsequently, we constructed a nomogram using WHO grade, chromosome 1p/19q codeletion, primary therapy outcome, IDH status, and TPM4 levels to predict 1-year OS, 2-year OS, and 3-year OS in patients with glioma." (PMID 36639743, 2023). "We found that the expression of TPM4 was upregulated in gliomas, and high TPM4 expression was related to a worse prognosis in gliomas." (PMID 36639743, 2023). "Next, we attempted to determine the expression level and prognostic value of the TPM4 gene in different clinical states of glioma." (PMID 36639743, 2023). "TPM4 is upregulated and related to the malignant characteristics of gliomas, possibly via epithelial-mesenchymal transition." (PMID 36993958, 2023). "For example, we found that the higher the tumor grade of the glioma, the higher its TPM4 expression." (PMID 36639743, 2023). "Our study showed that the mRNA and protein expression levels of TPM4 were significantly higher in glioma than in healthy brain tissue." (PMID 36639743, 2023). "Immunohistochemical results in the HPA database also demonstrated higher levels of TPM4 expression in gliomas compared to adjacent normal tissues at the protein level." (PMID 36639743, 2023). "We discovered that TPM4 was consistently upregulated in whole-grade glioma samples compared with healthy normal samples." (PMID 36639743, 2023). "Immune cell infiltration analysis revealed that high TPM4 expression in glioma was positively related to the levels of macrophages, neutrophils, and NK cells." (PMID 36639743, 2023). "Immunohistochemical staining of glioma samples also confirmed that the level of TPM4 in tumor tissues was higher than that in adjacent normal tissues." (PMID 36639743, 2023). "Univariate Cox analysis indicated that the high expression level of TPM4 in glioma was an independent prognostic characteristic for low overall survival (OS)." (PMID 36639743, 2023). "GSEA was conducted in each dataset further to demonstrate the biological function of TPM4 in gliomas." (PMID 36138856, 2022). "Our scRNA-seq analysis demonstrated that TPM4 was ubiquitously expressed on neoplastic cells, macrophages, oligodendrocytes, and T cells in glioma TME." (PMID 36138856, 2022). "In this study, a total of 998 patients with transcriptional data and clinical information were comprehensively analyzed, aiming to elucidate the clinical characterization and the potential biological mechanisms of TPM4 in glioma development." (PMID 36138856, 2022). "In conclusion, our findings indicate that TPM4 is significantly correlated with more malignant characteristics of gliomas, potentially through involvement in EMT." (PMID 36138856, 2022). "This study aimed to determine the clinical characterization and prognostic value of TPM4 in gliomas." (PMID 36138856, 2022). "In conclusion, TPM4 is closely related to more aggressive characteristics of glioma, and TPM4 upregulation predicts a shorter survival time for glioma patients." (PMID 36138856, 2022). "Our results revealed a significant relationship between TPM4 upregulation and more malignant phenotype in gliomas, including GBM, mesenchymal molecular-subtype, and IDH-wildtype glioma." (PMID 36138856, 2022). "Altogether, these results demonstrated that higher TPM4 expression was paralleled with more malignant clinical and pathophysiological characteristics in gliomas." (PMID 36138856, 2022). "No biological experiments were performed, and future molecular biological studies are required to validate the function of TPM4 in gliomas." (PMID 36138856, 2022). "The results showed that TPM1, TPM3, and TPM4 were significantly more highly expressed in glioma in comparison to normal tissues, while TPM2 mRNA expression showed no statistical differences." (PMID 35892971, 2022). "With regard to the histological types of glioma, high expressions of TPM3 and TPM4 were evidently associated with poorer prognosis in astrocytoma and oligodendroglioma." (PMID 35892971, 2022).
glioma (continued). "According to the median value of TPM4 expression, pan-glioma patients in both datasets were divided into two groups." (PMID 36138856, 2022). "The potential molecular function of TPM4 for gliomas was investigated based on TPM4-high-correlated genes." (PMID 36138856, 2022). "In this study, it was found that TPM1, TPM3, and TPM4 were significantly upregulated in gliomas, while a high expression level of TPM2, TPM3, and TPM4 was significantly correlated with poorer prognosis." (PMID 35892971, 2022). "When taking into account the molecular subtype, TPM4 expression was significantly upregulated in the mesenchymal subtype, which usually predicts a much worse survival status in glioma." (PMID 36138856, 2022). "To explore the TPM4 expression status in all gliomas, we took advantage of the CGGA dataset, including mRNA microarray data of whole-grade glioma." (PMID 36138856, 2022). "i-tRF-LeuCAA may indirectly regulate TPM4 expression and influence epithelial-mesenchymal transition, which may promote glioma progression." (PMID 40202170, 2025). "Therefore, STRING was used to analyze the TPM4 protein PPI networks to determine their interactions in glioma progression." (PMID 36639743, 2023). "We found that there were higher gene expression levels of TPM4 in glioma than in healthy samples." (PMID 36639743, 2023). "In addition, in the GEPIA dataset, we compared the TPM4 mRNA expression level between glioma (including GBM and LGG) and normal samples." (PMID 36639743, 2023). "Our findings suggest that TPM4 may be a novel and effective biomarker for glioma, offering new hope for improving the survival and prognosis of glioma patients." (PMID 36639743, 2023). "In conclusion, our study suggests that TPM4 may be an effective prognostic biomarker for glioma patients, providing new ideas and research directions for glioma research." (PMID 36639743, 2023). "In addition, we found that TPM4 expression was also related to IDH mutation status, chromosome 1p/19q codeletion, primary therapy outcome, and histological type in glioma patients." (PMID 36639743, 2023). "This may be closely related to the mechanism by which high TPM4 expression leads to a worse prognosis in glioma." (PMID 36639743, 2023). "Then, we analyzed TPM4 transcription levels in glioma by using TCGA and GEO data." (PMID 36639743, 2023). "Our results convincingly demonstrate that the TPM4 gene may play an important role in glioma immunity; therefore, TPM4-related research and novel targeted treatment may help improve the poor prognosis of glioma patients." (PMID 36639743, 2023). "However, their correlation with TPM4-related expression patterns, prognostic values, and the microenvironment of glioma tumors remains to be explored." (PMID 36639743, 2023). "The protein levels of TPM4 in glioma were explored using the HPA." (PMID 36639743, 2023). "Unveiling the biological function of TPM4 in glioma cells may facilitate a better understanding of the molecular mechanisms of gliomagenesis." (PMID 36138856, 2022). "High expression of TPM3 and TPM4 were positively correlated with poorer prognosis in glioma, and TPM3 could serve as a novel independent prognostic factor of glioma." (PMID 35892971, 2022). "This suggested that TPM4 and the TPM4-correlated genes might interact and play a synergistic effect in the remodeling of extracellular matrix, cell migration, and invasion of gliomas, in line with previous studies regarding other types of cancer." (PMID 36138856, 2022). "Taken together, our preliminary findings revealed that a high expression of TPM3 and TPM4 was strongly and positively correlated with poorer prognosis in glioma, and TPM3 could serve as a novel independent prognostic factor in glioma." (PMID 35892971, 2022). "Altogether, these results indicated that TPM4 could be identified as an effective prognosticator among Chinese and Caucasian patients with gliomas." (PMID 36138856, 2022).